SLC7A5P2 (solute carrier family 7 member 5 pseudogene 2)
Synonyms: IMAA; hLAT1-3TM
Gene: Transcribed processed pseudogene on chromosome 16 (21,519,830 to 21,520,365, reverse strand). Ensembl gene ENSG00000258186.
Subcellular location: Membrane
Diseases named in the same sentence as SLC7A5P2 in open-access papers:
SLC7A5P2 is named in the same sentence as 1 disease in open-access papers, as found by Europe PMC text mining. Sharing a sentence is not in itself a finding about the gene and the disease.
SLC7A5P2 shares sentences with these, for which no sentence is quoted: infection (1 paper).